SMAD4 (SMAD family member 4)
Diseases named in the same sentence as SMAD4 in open-access papers (continued):
Sharing a sentence is not in itself a finding about the gene and the disease.
tumor (continued). "Analysis of a cohort of 364 patients with stage I–IV CRC showed that SMAD4 deficiency was associated with higher tumour and nodal staging, the use of adjuvant therapy, fewer tumour infiltrating lymphocytes (TIL), lower peritumour lymphocyte aggregation (PLA) scores, and poorer RFS." (PMID 37685308, 2023). "PTEN (Phosphatase and Tensin homolog) is a tumor suppressor gene related to SMAD4 function; the loss of its expression/function may be related to cancer aggressiveness." (PMID 37687058, 2023). "SMAD4 acts as a tumor suppressor and its loss is associated with poorer patient outcomes." (PMID 37377893, 2023). "Moreover, Smad4 deletion in murine tissues, in combination with other genetic alterations that cause tumor initiation, resulted in cancer lesions of the colon, pancreas, stomach, and liver." (PMID 38003328, 2023). "It is hypothesised that heterozygous loss-of-function (LOF) SMAD4 mutations may prevent formation of these complexes, thus promoting growth, resulting in cellular proliferation and subsequently neoplasia." (PMID 38066625, 2023). "Nevertheless, the tumors deficient for Smad4 retained epithelial differentiation and manifested an attenuated metastatic potential, which is also in favor of a tumor promoter role of TGF-β signaling." (PMID 36828547, 2023). "However, similar to our results, loss of SMAD4 in tumor and stroma was correlated with high grade tumors." (PMID 36900240, 2023). "Thus, SMAD4/DPC4 deficiency promotes PDAC immunogenicity through the induction of type I interferon signalling triggered by intrinsic tumour DNA damage." (PMID 37685308, 2023). "Increased tumor number and mass were observed in Smad4‐deficient mice." (PMID 37261975, 2023). "Functionally relevant mutations in alternative SMAD4 promoters were shown to be quite rare, so in the case of this tumor suppressor other mechanisms and interactions with the cellular proteotranscriptome may be more relevant." (PMID 35034624, 2022). "Indeed, we and others have previously shown that epithelial-specific loss of Tgfbr1/2 or Smad4 accelerates tumourigenesis in the context of Apc and Kras mutations, consistent with key tumour-suppressive roles for epithelial TGFβ signalling in CRC." (PMID 36477656, 2022). "We next explored how Smad4 deficiency in tumor cells increased MHC‐I expression." (PMID 35064757, 2022). "Unexpectedly, Smad4 deficiency significantly impaired tumor growth in immune‐competent B6 mice." (PMID 35064757, 2022). "Furthermore, tumor suppressor genes with a mutational frequency of >10% in cell lines involved SMAD4, SMARCA4, ARID1A, ARID2, and RBM10." (PMID 36013219, 2022). "Mutations of SMAD4 promote dysregulation of NK cell homeostasis and augment tumor cell metastases." (PMID 35461253, 2022). "Based on immunohistochemical and statistical analysis, we found that Smad4 expression was associated with higher tumor grade (p=0.048), and TIF1-γ expression was also associated with tumor grade (p=0.014), with lower protein expression being associated with lower tumor grade." (PMID 35251569, 2022). "To determine whether loss of SMAD4 has a direct effect on tumor cytokine synthesis, we first used the established SMAD4-intact PDAC cell line PANC-1." (PMID 35155243, 2022). "’s cohort were of stage IV, which may affect SMAD4 mutation prevalence as loss of SMAD4 can lead to tumor metastases." (PMID 35180847, 2022).
tumor (continued). "However, the effect of Smad4 loss on the immunogenicity and tumor immune microenvironment of PDAC is still unclear." (PMID 35064757, 2022). "Thus, loss of SMAD4 tumor suppressive activity in PDAC leads to an oncogenic gain-of-function of SMAD2/3, and to the onset of associated deleterious effects." (PMID 36207615, 2022). "Furthermore, retarded tumor growth of Smad4‐deficient PDAC cells on B6 mice is largely reversed when Sting is codeleted, or when the cells are implanted into interferon‐alpha receptor‐deficientmice or cDC1‐deficientmice." (PMID 35064757, 2022). "Increased level of spontaneous DNA damage in SMAD4‐deficient PDAC cells stimulated STING‐mediated IFN‐I signaling to promote tumor cell major histocompatibility complex‐I (MHC‐I) expression and cDC1‐mediated antigen cross‐presentation, which together boosted antitumor immunity." (PMID 35064757, 2022). "Taken together, these findings indicate that SMAD4 is a crucial tumor suppressor and that its mutation might be involved in several cancer cell biological functions, including maintaining cancer genome stability and regulating the cell cycle and apoptosis." (PMID 36142267, 2022). "Smad4 mutations also correlate with tumour formation and may predict poor prognosis and aggressive tumour phenotypes." (PMID 36267157, 2022). "The overexpression of SMAD4 in SMAD4-deficient tumor cells inhibits tumorigenesis." (PMID 35720407, 2022). "Additionally, the effectiveness of PARP inhibition in the radiosensitisation of HNSCC cells and tumours has been linked with SMAD4 involved in TGFβ signalling and where SMAD4-deficient models were shown to be more responsive to the combined treatment." (PMID 36052247, 2022). "Thus, loss of the SMAD4 tumor suppressor in PDAC is associated with altering sEV secretion and cargo content to generate an immunosuppressive TME." (PMID 34638330, 2021). "Such approaches may thus be effective against SMAD4-deficient tumours harbouring elevated BMPR levels that presently confer a worse prognosis, compared with counterparts exhibiting low BMPR expression." (PMID 33673710, 2021). "In addition, the positivity of two proliferative markers, Ki‐67 and PCNA, was also lessened in tumours with circ_SMAD4 deficiency." (PMID 33458917, 2021). "Chromotripsis in EAC can also lead to the loss of tumor suppressors such as SMAD4." (PMID 34503107, 2021). "This may indicate a role for delivery of HCQ especially to patients with SMAD4 loss in order to improve tumor resectability and inform patient selection for future studies on HCQ or other emergent and experimental autophagy inhibitors." (PMID 34002944, 2021). "While PANC11 had undetermined tumour content, a junction predicted loss of SMAD4." (PMID 33704908, 2021). "Hence, this study aimed to investigate methylation patterns of both PTEN and SMAD4 among primary BC patients and compare their role with other non-cancer groups as well as assess their diagnostic effectiveness with other tumor markers (CEA and CA15.3)." (PMID 33825073, 2021). "An earlier study by Oshima suggested that mutations in SMAD4 were significantly associated with tumor size, lymphatic infiltration, and lymph node metastasis, whereas CDKN2A mutations were associated with lymphatic infiltration and extensive postoperative metastasis." (PMID 35127473, 2021). "Chromosome 18 contains the gene encoding the SMAD4 protein that mediates TGFβ signaling and the SMAD4 gene is frequently mutated in several types of malignant tumors resulting in altered TGFβ signaling and thereby promoting tumor progression and metastatic capacity." (PMID 33509126, 2021).
tumor (continued). "In addition, numerous reports suggest that Smad4 deficiency drives cancer metastasis and tumor malignancy." (PMID 31243343, 2020). "Indeed, some studies have shown that BMP signaling changes from tumor suppressing to tumor promoting upon loss of SMAD4." (PMID 32486027, 2020). "However, the mechanisms by which loss of Smad4 contributes to tumor progression and metastasis are poorly understood and they are likely complex, given the tissue-specific roles of Smad4 signaling and the multiple processes that it regulates." (PMID 33424832, 2020). "Moreover, RNF11 can directly enhance TGFb signaling through a direct association with SMAD4 and promote the malignant development of tumor cells." (PMID 33123581, 2020). "Smad4 and Pten belong to the most frequently mutated tumor suppressor genes in CCA." (PMID 32679791, 2020). "SMAD4 inactivation is implicated in tumor malignancy and resistance to multiple drugs." (PMID 33089107, 2020). "BCL2L11 is a tumor suppressor, it is an important regulator of apoptosis; loss of the SMAD4 activity may disrupt DNA damage response and repair mechanisms and enhance genomic instability." (PMID 31540229, 2019). "The loss of SMAD4 function, known to trigger tumor progression and metastasis, may explain the high proliferative potential of R1 organoids." (PMID 30925167, 2019). "The loss of SMAD4 protein contributes to an increase in genomic instability in the tumor epithelia." (PMID 31867281, 2019). "Consistent with the hypothesis of a similarity between the pro-tumor effects of TGFβ and MG stress is the loss of SMAD4, which has been shown to abolish TGFβ tumor-suppressive functions while maintaining its role as an EMT inducer." (PMID 30674353, 2019). "To investigate whether the SMAD4-deleted tumors were biased towards a more aggressive subtype, we ranked SMAD4 gene deletions and mutations by the histological grades and tumor stages." (PMID 31569425, 2019). "Functional analysis of a missense mutation in the MH1 domain of SMAD4 may be responsible for the loss of function in suppressing tumor progression." (PMID 31867281, 2019). "Consequently, SMAD4’s role as a tumor suppressor can be identified using both DNA mutant allele frequencies and RNA mutant allele frequencies." (PMID 31484939, 2019). "Interestingly, a recently published retrospective analysis of human colorectal tumors demonstrated that loss of SMAD4 expression was associated with lower tumor infiltration lymphocytes and a trend towards decreased peritumoral lymphocyte aggregates." (PMID 33834163, 2019). "Furthermore, the results of our studies demonstrate that SMAD4 loss due to mutations and downregulation results in increased tumor progression and recurrence rates." (PMID 31867281, 2019). "This study showed that, upon up-regulation of HLA class I and APM expression through IFN-γ treatment of CSCs/CICs, T cells could specifically recognize a neoantigen, SMAD4, generated by a non-synonymous mutation bearing stem-like cells and bulk tumor cells." (PMID 31758404, 2019). "Moreover, we investigated the role of deleterious SMAD4 mutations to elucidate their role in HNSCC neoplasms." (PMID 31867281, 2019). "The loss of SMAD4 is contributing to increased genomic instability in the tumor epithelia." (PMID 31867281, 2019). "Multiple factors including the viability of the primary tumor sample, the sterility of the tumor handling and the genetic mutation status (such as Smad4 loss) determine successful engraftment of patient tumor tissue following xenotransplantation into immunodeficient mice." (PMID 30744205, 2019). "The mechanism is unknown but a study of in vitro CRC cell lines has implicated the effects of SMAD4 expression on tumor microenvironment." (PMID 30730996, 2019). "For instance, mutations in DPP homolog 4 (SMAD4) in humans is hypothesized to promote epithelial b1-integrin mechanosignaling, leading to matricellular fibrosis, increased tissue tension, and tumor progress." (PMID 32601597, 2019).
tumor (continued). "They reported that depleting ME3 selectively killed ME2-null PDAC cells, and so hypothesised potential new specific targets for novel inhibitors in SMAD4-mutated tumours." (PMID 29329208, 2018). "In addition, loss of Smad4 results in enhanced tumor growth and anti-apoptotic pathways, and increased lymph node metastasis in xenograft models." (PMID 29735981, 2018). "The analysis of various mutant combinations allowed the determination that the initiating APC and KRAS mutations act as the drivers of proliferation and tumor growth, while inactivating mutations in SMAD4 block differentiation during tumor growth and being required for metastatic potential." (PMID 29652830, 2018). "Mechanistically, these mutations tend to disrupt the original protein function, exemplified by the disrupted substrate binding in CREBBP and EP300, or to prevent the activation of a tumor suppressor, exemplified by mutations within the SMAD4 interface or CHEK2 activation loop (Dataset EV5)." (PMID 29572294, 2018). "Since NF-kB regulates multiple anti-apoptotic genes and is considered to be a major contributor to radioresistance, it is possible that simultaneous mutations in KRAS and SMAD4 (as observed in the present study) contributed to the radioresistant nature of the tumor via this mechanism." (PMID 30220971, 2018). "Solving the mystery of the molecular interactions with other oncogenic signaling pathways associated with SMAD4 independent TGF-β signaling will provide great insight into the functional switch of TGF-β from a tumor suppressor to a promotor of tumor development." (PMID 29467938, 2018). "SMAD4 is a tumor suppressor encoded by the SMAD4 gene located on chromosome 18q." (PMID 28099906, 2017). "However, patients showing a loss of SMAD4 expression in their tumor tissue had a statistically significantly longer PFS than patients with preserved SMAD4 expression (median 7.0 vs. 5.8 months, p = 0.038)." (PMID 28534865, 2017). "As CRC progresses into later stages, TGF-ß switches from functioning as a tumor suppressor to a tumor promoter, and SMAD4 loss may be involved in this shift." (PMID 28423626, 2017). "In addition to SMAD4 mutation status, variables associated with OS in univariate Cox regression analysis were Hispanic ethnicity and poor tumor differentiation." (PMID 28267766, 2017). "In fact, patients showing a loss of SMAD4 in their respective tumor tissue had a significantly better PFS than patients with SMAD4-positive tumors, most notably in the gemcitabine-treated subgroup where the SMAD4 status actually was an independent prognostic factor for PFS." (PMID 28534865, 2017). "Indeed, the mice carrying both mutations in Apc and Smad4 developed more malignant tumours, highlighting the role of BMP inactivation in tumour progression." (PMID 28059064, 2017). "With tumor progression, tumor cells can acquire resistance to TGF-β growth inhibition by downregulation or mutation of the TGF-β receptors (TGF-βR) or TGF-β pathway downstream effectors such as Smad4, a coactivator in the canonical TGF-β pathway." (PMID 28098775, 2017). "Demographic and tumor characteristics of CRC patients according to SMAD4 mutation status." (PMID 28267766, 2017). "Other mechanisms (e.g. loss of SMAD4 or of the tumor suppressor p15INK4B) could also be involved in the resistance to the anti-tumor effect of ActA, as it was shown in other types of cancer." (PMID 26950277, 2016).
tumor (continued). "The mechanism underlying the tumour suppressor function is thought to be Smad4-independent." (PMID 26624618, 2015). "Fewer frequencies of SMAD4 mutation in BCBM may be attributed that SMAD4 plays a dual role in carcinogenesis, being a tumor suppressor and a tumor promoter in different stages, although further investigations are necessary to confirm these findings." (PMID 26527317, 2015). "Amplification of the oncogene KRAS and loss of tumour suppressor SMAD4 may fuel cancer progression in this tumour." (PMID 25351503, 2014). "Moreover, it was found that Smad4 was associated with tumor invasion, metastasis and prognosis in different cancers." (PMID 25333693, 2014). "In the context of tumour progression, SMAD4 loss-of-function may not only be necessary for counteracting TGF-β anti-proliferative effects, but may also contribute to rewiring the cells' processing system, translating TGF-β input signals into different outputs." (PMID 24393789, 2014). "SMAD4 is a tumor suppressor implicated in multiple cancer types including OSCC." (PMID 23826135, 2013). "Loss of Smad4 might underlie the functional shift of TGF-β from a tumor suppressor to a tumor promoter." (PMID 23443093, 2012). "Mutations in tumour suppressor SMAD4 were observed in ten samples." (PMID 21781349, 2011). "Briefly, SMAD4 deletion enhanced PAC pathogenesis directed by KRAS mutation, but also altered the tumor phenotype: tumors with SMAD4 deficiency were well-to-moderately differentiated and expressed epithelial markers, whereas tumors with intact SMAD4 frequently exhibited markers of EMT." (PMID 24212636, 2011). "Similar to Smad4, normal pancreatic tissue showed moderate to high levels of Smad7 expression in most of the samples (18/25, 72%), whereas, more than half of tumor tissue showed complete loss of protein expression (4/25, 56%), and another 24%(6/25) of cases showed low expression." (PMID 22195733, 2011). "In the present study we show that loss of the tumor suppressor Smad4 may be one of the molecular mechanisms that can lead to this relative overexpression of the laminin-γ2 chain in response to the inflammatory cytokine TNFα." (PMID 20307265, 2010). "In conclusion, we here suggest a novel mechanism that may underlie the switch to invasive tumor growth upon loss of the tumor suppressor Smad4." (PMID 20307265, 2010). "We employed Smad4 genetically null cells, whereas previous studies analysed the consequences of knock-down of Smad4 using RNAi or profiled tumour cell lines, in all likelihood carrying multiple mutations that could potentially complicate the analysis." (PMID 19849841, 2009). "Down-regulation of the Igfbp3 gene, encoding for the insulin growth factor binding protein, in Smad4+/E6sad ES and intestinal cells may also represent a relevant early step in tumor formation." (PMID 19014666, 2008). "We hypothesize that this divergence in modular regulation of the three promoters may lay the ground for uncoupled regulation of Laminin-332 in Smad4-deficient tumor cells in response to stromally expressed cytokines acting on budding tumor cells." (PMID 18664273, 2008). "Moreover, the employment of normal rather than neoplastic cells allows bypassing of confounders caused by the altered cellular physiology characteristic of tumor cells and focuses on the primary molecular and cellular consequences of Smad4 haploinsufficiency." (PMID 19014666, 2008). "The heterologous reexpression of Smad4 in Smad4-deficient cancer cell lines could reduce tumor growth in vivo." (PMID 17997817, 2007). "We conclude that Smad4 effects on the composition of extracellular matrix may underlie its tumor suppressive activity." (PMID 17997817, 2007). "However, pooling of the groups WHO stage I and II as well as WHO stage III and IV again showed a trend toward a positive influence of Smad4 loss on 5-year survival that was pronounced in advanced tumor stages." (PMID 16438724, 2006).